PLCZ1 (phospholipase C zeta 1)
Description:
The production of the second messenger molecules diacylglycerol (DAG) and inositol 1,4,5-trisphosphate (IP3) is mediated by activated phosphatidylinositol-specific phospholipase C enzymes. In vitro, hydrolyzes PtdIns(4,5)P2 in a Ca(2+)-dependent manner. Triggers intracellular Ca(2+) oscillations in oocytes solely during M phase and is involved in inducing oocyte activation and initiating embryonic development up to the blastocyst stage. Is therefore a strong candidate for the egg-activating soluble sperm factor that is transferred from the sperm into the egg cytoplasm following gamete membrane fusion. May exert an inhibitory effect on phospholipase-C-coupled processes that depend on calcium ions and protein kinase C, including CFTR trafficking and function.
Synonyms: PLC-zeta-1; NYD-SP27; PLCzeta; Czeta; SPGF17
Tractability: No criterion of Open Targets' tractability assessment is met for any kind of drug.
Target class: Enzyme; Hydrolase
Gene: Protein-coding gene on chromosome 12 (18,683,169 to 18,738,100, reverse strand). Ensembl gene ENSG00000139151.
Subcellular location: Nucleus; Cytoplasm, perinuclear region; Cytoplasmic vesicle, secretory vesicle, acrosome
Pathways (Reactome):
Metabolism: Synthesis of IP3 and IP4 in the cytosol
Gene Ontology:
Molecular function: phosphatidylinositol-3-phosphate binding; phosphatidylinositol-4,5-bisphosphate binding; phosphatidylinositol-4,5-bisphosphate phospholipase C activity; phosphatidylinositol-5-phosphate binding; calcium ion binding; phospholipase C activity; phosphoric diester hydrolase activity
Biological process: egg activation; positive regulation of cytosolic calcium ion concentration; positive regulation of cytosolic calcium ion concentration involved in egg activation; intracellular signal transduction; lipid metabolic process; signal transduction
Cellular component: nucleus; sperm head; acrosomal vesicle; cytosol; cytoplasm; nucleolus; nucleoplasm; perinuclear region of cytoplasm; pronucleus
Genetic constraint (gnomAD): Loss-of-function variants: 53 observed, 69.06 expected, observed/expected ratio (o/e) 0.77, 90% interval 0.62 to 0.96. The upper end of that interval is the gene's LOEUF score, 0.96, which puts it in group 4 of 6, group 1 being the genes least tolerant of losing a copy. Missense variants: 671 observed, 644.35 expected, observed/expected ratio (o/e) 1.04, 90% interval 0.98 to 1.11. Synonymous variants: 221 observed, 210.92 expected, observed/expected ratio (o/e) 1.05, 90% interval 0.94 to 1.17.
Homologues: Orthologues: chimpanzee PLCZ1 (99% identical), macaque PLCZ1 (95% identical), pig PLCZ1 (83% identical), rabbit PLCZ1 (82% identical), dog PLCZ1 (82% identical), guinea pig PLCZ1 (80% identical), mouse Plcz1 (75% identical), rat Plcz1 (74% identical), Caenorhabditis elegans plc-3 (35% identical), Caenorhabditis elegans pll-1 (34% identical), Drosophila melanogaster Plc21C (34% identical), Caenorhabditis elegans plc-4 (31% identical), and 1 more. Paralogues in human: PLCD4 (44% identical), PLCD1 (41% identical), PLCH2 (40% identical), PLCH1 (40% identical), PLCL2 (39% identical), PLCD3 (39% identical), PLCL1 (38% identical), PLCE1 (35% identical), PLCB1 (35% identical), PLCB4 (35% identical), PLCB2 (34% identical), PLCB3 (34% identical), and 2 more.
Diseases named in the same sentence as PLCZ1 in open-access papers:
PLCZ1 is named in the same sentence as 10 diseases in open-access papers, as found by Europe PMC text mining. Sharing a sentence is not in itself a finding about the gene and the disease. The quoted sentences say what the papers report.
male infertility (17 papers, 2014 to 2026). The inability of the male to effect fertilization of an ovum after a specified period of unprotected intercourse. "Mutations in PLCZ1 are increasingly recognized as a significant genetic cause of male infertility, particularly in individuals presenting with fertilization failure following assisted reproductive techniques such as intracytoplasmic sperm injection (ICSI)." (PMID 40429849, 2025). "This study elucidated the pathogenic mechanism of PLCZ1 variation and the genetic diagnosis of male infertility due to TFF, especially in the normozoospermic sperm sample." (PMID 39042720, 2024). "Mutations of Plcz1 in human sperm reduce oocyte activation, indicating male infertility, and fertility was restored in most of these individuals after ICSI by an injection of Plcz1 RNA or an activation treatment such as Ca2+ ionophore and SrCl2." (PMID 38540777, 2024). "Clinical trial.PLCZ1 mutations and impaired PLCZ1 protein was associated with male infertility.AOA improved fertilization in men carrying PLCZ1 mutations." (PMID 38133249, 2023). "In conclusion, this study provided novel mutations in PLCZ1 gene to expand the pathogenic mutational spectrum in male infertility and demonstrated that PLCZ1 was a crucial sperm-related genetic factor for early embryonic arrest." (PMID 37261077, 2023). "In humans, mutations in PLCZ1 genes cause male infertility and fertilization failure of intracytoplasmic sperm injection (ICSI)." (PMID 38203456, 2023). "Most cases of oocyte activation failures in humans related to male infertility are associated with gene mutations and/or altered PLCZ1." (PMID 38133249, 2023). "In human assisted reproduction, PLCZ1 characterization is of essential importance when oocyte activation failures are linked to male infertility." (PMID 38133249, 2023). "If there is male infertility involving eCS, it would be in patients with normal PLCZ1 expression and age-dependent loss of fertility." (PMID 38203456, 2023). "In humans, 30–40% of fertility failure after ICSI is caused by male infertility linked to impaired gene sequence or protein content, localization, and function of PLCZ1." (PMID 38133249, 2023). "In this study, among four PLCZ1-related infertile male patients, we identified three novel pathogenic mutations, which expanded the mutational spectrums of PLCZ1 that caused male infertility." (PMID 37261077, 2023). "The association between sperm PLCZ1 and male infertility in assisted fertilization has been experimentally and clinically established in humans and horses." (PMID 38133249, 2023). "Following the discovery of PLCZ1, a substantial body of evidence has confirmed the indispensable role of PLCZ1 in oocyte activation and clearly demonstrated that the expression and localization of PLCZ1 in human sperm are associated with male infertility." (PMID 35312629, 2022). "The impact of these factors on PLCZ1 expression may cause the dysfunction of PLCZ1 protein and therefore male infertility." (PMID 38279344, 2024). "In addition, it has been indicated that male infertility in humans depends on the genetic mutation of Plcz1−/−, which causes a loss of calcium oscillations, resulting in failed pregnancy after ICSI." (PMID 37109509, 2023). "Furthermore, some reports have shown that levels of PLCZ1 protein and mutations in the gene encoding PLCZ1, are strongly associated with male infertility/subfertility." (PMID 35312629, 2022). "Furthermore, missense mutations within human PLCz1 confer male infertility." (PMID 25354211, 2014). "This study enhances the potential for genetic diagnosis of male infertility due to TFF, thus expanding the spectrum of genetic causes associated with PLCZ1." (PMID 39042720, 2024). "Investigations should explore the possibility that variations in these elements can compromise PLCZ1 expression, potentially leading to the malfunction of the PLCZ1 protein and male infertility." (PMID 38279344, 2024).
male infertility (continued). "The relationship between male infertility and PLCZ1 in men has been confirmed in several clinical and experimental studies." (PMID 38133249, 2023). "PLCZ1 is expressed in sperm, and variations of this gene lead to low fertilization and male infertility." (PMID 26308735, 2015). "It would be therefore very interesting if future studies investigate whether abnormalities in these factors can impair PLCZ1 expression, which eventually contributes to the dysfunction of the PLCZ1 protein and male infertility." (PMID 35312629, 2022). "Otherwise, eCS dysfunction in the sperm may explain age-dependent male infertility in the presence of PLCZ1." (PMID 31857692, 2020).
infertile (15 papers, 2014 to 2026). "It has been reported that ICSI combined with AOA is effective for infertile men with PLCZ1 mutations, which can partially rescue fertilization failure and contribute to successful pregnancy mainly due to oocyte activation failure (OAF." (PMID 40794537, 2025). "In this study, a novel PLCZ1 compound heterozygous mutation was found in an infertile male who experienced repeated fertilization failure even after ICSI-AOA by whole exome sequencing." (PMID 40794537, 2025). "Several clinical studies have documented mutations in the PLCZ1 gene in infertile men who experience recurrent fertilization failures." (PMID 40572651, 2025). "A previous study introduced two mutations into mice, i.e., H435P (a mutation corresponding to human H398P) and D210R (an enzymatic dead mutation), in order to investigate the mechanism of infertility caused by point mutations in Plcz1 reported in humans." (PMID 38540777, 2024). "In a case study, a novel homozygous PLCZ1 nonsense mutation, c.588C > A (p.Cys196Ter) has been found in an infertile man with FF." (PMID 38279344, 2024). "All previous Plcz1 mutations have been single missense mutations, but compound heterozygous mutations in Plcz1 were identified in an infertile male patient." (PMID 38540777, 2024). "Here, we reported bi-allelic mutations in PLCZ1, a well-known causal gene of total fertilization failure, in four infertile males." (PMID 37261077, 2023). "FF, characterized as failure to form two-pronucleus (2 PN) zygotes with morphologically normal gametes even with the help of ICSI, was a typical phenotype of infertile men carrying bi-allelic mutations in PLCZ1." (PMID 37261077, 2023). "It has been reported that one-third of infertile men suffering from FF carry mutations in PLCZ1 gene." (PMID 37261077, 2023). "Expanding the mutational spectrum of PLCZ1 helps to provide theoretical support for more infertile men." (PMID 37261077, 2023). "This discovery was significant as it demonstrated for the first time that PLCZ1 can be inherited maternally, and that this could result in a loss of sperm function in the son and subsequently in infertility." (PMID 38279344, 2024). "However, the polyspermy phenotype was most recently reported in only one study, which presented an infertile male with a homozygous PLCZ1 mutation." (PMID 37261077, 2023). "Here, we identified bi-allelic PLCZ1 mutations in four infertile males, including three novel variants (c.T1466G, p.I489S), (c.1208_1213del, p.403_404del) and (c.C1607T, p.W536X), which expanded the pathogenic mutational spectrum of PLCZ1 gene." (PMID 37261077, 2023). "Importantly, this study suggests a strategy to test the efficacy and safety of recombinant Plcz1 protein as an alternative therapeutic agent to treat infertility caused by Plcz1 deficiency." (PMID 36613757, 2022). "Screening of the gene encoding PLCZ1 protein is also critical if we are to fully determine the extent to which genetic factors might play a role in the aberrant expression and/or localization patterns observed in infertile patients." (PMID 35312629, 2022). "Screening of the gene encoding the PLCZ1 protein is also critical if we are able to fully determine the extent to which genetic factors might play a role in the aberrant expression and/or localization patterns observed in infertile patients." (PMID 35312629, 2022). "The considerable variance in sperm PLCZ1 resultants of assessments of infertile men subjected to ICSI cannot be efficiently discriminated from fertile men, leading to a weak or null association with fertility after ICSI." (PMID 38133249, 2023). "In some cases, the PLCZ1 content and localization pattern of fertile men were similar to those of infertile men with recurrent oocyte activation failure." (PMID 38133249, 2023).
infertile (continued). "The database showed that the carrier frequencies of the expected/known pathogenic variants in PLCZ1 were higher in East Asian population compared with those in total population, suggesting the important role of PLCZ1 gene in Chinese infertile male patients." (PMID 37261077, 2023). "When associated with infertility in men, oocyte activation failure after ICSI has been attributed to PLCZ1 mutations or protein alterations in 30 to 40% of failures." (PMID 38133249, 2023). "In our study, we found that infertile men presenting with less than 71% of their sperm containing PLCZ1 and with a mean PLCZ1 level of 15.57 arbitrary are most likely to benefit from AOA treatment." (PMID 35312629, 2022). "In the past decade, male mice with sperm Plcz1 defects were found to exhibit malformed sperm and infertility." (PMID 36613757, 2022). "To date, 24 PLCZ1 variants associated with poor or failed fertilization after IVF/ICSI attempts have been identified using Sanger sequencing and WES in infertile men." (PMID 36589837, 2022). "Of most concern was the fact that some infertile patients clearly exhibited lower levels of PLCZ1 than fertile controls." (PMID 35312629, 2022). "These variations in PLCZ1 content between the ejaculates of fertile and infertile men raise significant questions as to why such disparity occurs." (PMID 35312629, 2022). "Immunofluorescent assays of the expression levels and localization patterns of PLCZ1 have indicated significant variation among both fertile and infertile patients." (PMID 35312629, 2022). "Our findings, together with extant knowledge of PLCZ1 gene, might benefit the genetic counseling of infertile men in the future, and provide them with more rational ART strategies to increase the live birth rate." (PMID 37261077, 2023). "Besides, more cases were reported to further verify the polyspermy phenotype in PLCZ1-related infertility." (PMID 37261077, 2023). "As discussed extensively in this review, both fertile and infertile men are known to exhibit variable PLCZ1 levels; therefore, is it important that we consider both levels and the proportion of sperm containing the PLCZ1 protein before making a clinical decision." (PMID 35312629, 2022). "By using the algorithm, our laboratory-based in-house PLCZ1 assay can evaluate PLCZ1 expression in infertile males, therefore identifying whether the state of infertility is male-related." (PMID 35312629, 2022). "In line with this, the infertile patient who exhibited the C196X mutation showed no PLCZ1 expression in his sperm." (PMID 35312629, 2022). "In infertile men, defects in expression and abnormal patterns of PLCz1 were observed." (PMID 25354211, 2014). "Therefore, abnormalities in PLCZ1 conformation can lead to infertility." (PMID 40331949, 2025). "Accordingly, sperm from infertile males with teratozoospermia (abnormal head morphology) have previously been demonstrated to exhibit abnormal localization or the absence of PLCZ1 but showed a variance in PLCZ1 expression in comparison to controls." (PMID 35312629, 2022).
varicocele (2 papers, 2025). A condition characterized by the dilated tortuous veins of the spermatic cord with a marked left-sided predominance. "TP53I11 and EDDM3B were also associated with Sertoli cell-only syndrome and TEX101, EDDM3B, and PLCZ1 with varicocele." (PMID 40497989, 2025).
cryptorchidism (1 paper, 2023). The failure of one or both testes of a male fetus to descend from the abdomen into the scrotum during the late part of pregnancy. "According to the extent of difference between cryptorchidism and normal testis, the expression of seven downregulated genes (PLCZ1, AKAP4, AKAP3, IZUMO1, SPAG6, CAPZA3, and ROPN1L) were further selected for validation by qPCR." (PMID 38027210, 2023).
fertilization disorder (1 paper, 2025). "In this paper, we report a fertilization disorder caused by a PLCZ1 gene mutation." (PMID 40794537, 2025).
Globozoospermia (1 paper, 2022). Any structural anomaly of the acrosome resulting in a round sperm head. "This is not surprising as an individual with DPY19L2-dependent globozoospermia was found to produce defective sperm featuring loss of the acrosome and surrounding materials including PLCZ1." (PMID 35312629, 2022).
oligospermia (1 paper, 2017). Decreased number of spermatozoa in the semen. "Three down-regulated genes (PLCZ1, TSSK2 and ANKRD7) were common between MArrest, oligospermia and the Dazap1 mouse mutant." (PMID 29150651, 2017).
PLCZ1 also shares sentences with these, for which no sentence is quoted: Obesity (1 paper); Sertoli Cell-Only Syndrome (1); teratozoospermia (1).